POC1B-GALNT4 (POC1B-GALNT4 readthrough)
Gene: Protein-coding gene on chromosome 12 (89,519,408 to 89,526,262, reverse strand). Ensembl gene ENSG00000259075.
Genetic constraint (gnomAD): Loss-of-function variants: 24 observed, 44.43 expected, observed/expected ratio (o/e) 0.54, 90% interval 0.39 to 0.76. The upper end of that interval is the gene's LOEUF score, 0.76, which puts it in group 3 of 6, group 1 being the genes least tolerant of losing a copy. Missense variants: 727 observed, 694.34 expected, observed/expected ratio (o/e) 1.05, 90% interval 0.98 to 1.11. Synonymous variants: 249 observed, 247.6 expected, observed/expected ratio (o/e) 1.01, 90% interval 0.91 to 1.12.